COL6A6 (collagen type VI alpha 6 chain)
Description:
Collagen VI acts as a cell-binding protein.
Tractability: Antibody: its Gene Ontology location is reachable by antibodies, with high confidence; UniProt places it where antibodies can reach, with medium confidence; UniProt predicts a signal peptide or a membrane-spanning region. PROTAC: ubiquitination databases record sites on it. Other modalities: an approved drug acts on it.
Gene: Protein-coding gene on chromosome 3 (130,517,177 to 130,677,044, forward strand). Ensembl gene ENSG00000206384.
Subcellular location: Secreted, extracellular space, extracellular matrix
Pathways (Reactome):
Extracellular matrix organization: Assembly of collagen fibrils and other multimeric structures; Collagen biosynthesis and modifying enzymes; Collagen chain trimerization; Collagen degradation; ECM proteoglycans; Integrin cell surface interactions
Developmental Biology: NCAM1 interactions
Signal Transduction: Signaling by PDGF
Gene Ontology:
Molecular function: extracellular matrix structural constituent conferring tensile strength
Biological process: extracellular matrix organization
Cellular component: extracellular matrix; collagen type VI trimer; extracellular region
Genetic constraint (gnomAD): Loss-of-function variants: 141 observed, 155.5 expected, observed/expected ratio (o/e) 0.91, 90% interval 0.79 to 1.04. The upper end of that interval is the gene's LOEUF score, 1.04, which puts it in group 4 of 6, group 1 being the genes least tolerant of losing a copy. Missense variants: 2,496 observed, 2,572.5 expected, observed/expected ratio (o/e) 0.97, 90% interval 0.94 to 1. Synonymous variants: 874 observed, 945.81 expected, observed/expected ratio (o/e) 0.92, 90% interval 0.87 to 0.98.
Homologues: Orthologues: chimpanzee COL6A6 (99% identical), macaque COL6A6 (95% identical), rat Col6a6 (83% identical), guinea pig COL6A6 (83% identical), mouse Col6a6 (83% identical), rabbit COL6A6 (82% identical), pig COL6A6 (79% identical), tropical clawed frog col6a6 (45% identical), zebrafish col6a4a (36% identical), zebrafish col6a4b (26% identical). Paralogues in human: COL6A5 (54% identical), COL6A3 (31% identical), COL12A1 (18% identical), COL14A1 (15% identical), MATN2 (8% identical), VWA2 (8% identical), MATN4 (7% identical), MATN1 (6% identical), VIT (5% identical), COCH (5% identical), MATN3 (4% identical), VWA1 (3% identical).
Diseases named in the same sentence as COL6A6 in open-access papers:
COL6A6 is named in the same sentence as 38 diseases in open-access papers, as found by Europe PMC text mining. Sharing a sentence is not in itself a finding about the gene and the disease. The quoted sentences say what the papers report.
pituitary adenoma (6 papers, 2019 to 2023). "P4HA3 is located upstream of the PI3K/AKT signaling pathway, and type VI α6 collagen (COL6A6) interacts with P4HA3 to inhibit pituitary adenoma (PA) growth and metastasis by blocking the PI3K/AKT signaling pathway." (PMID 37035741, 2023). "P4HA3 reverses the inhibitory effect of COL6A6 on EMT in pituitary adenoma (PA)." (PMID 37035741, 2023). "Furthermore, in pituitary adenoma tissues, COL6A6 reportedly inhibited cancer progression by inhibiting the PI3K-AKT pathway." (PMID 33562096, 2021). "Long et.al reported that COL6A6 interacted with P4HA3 to suppress the growth and metastasis of pituitary adenoma via blocking the PI3K-Akt pathway." (PMID 35488336, 2022). "Mechanically, COL6A6 interacted with P4HA3 to suppress the growth and metastasis of pituitary adenoma via blocking PI3K-Akt pathway." (PMID 31627190, 2019). "The role and mechanism of collagen type VI alpha 6 (COL6A6) on tumor growth and metastasis in pituitary adenoma (PA) was determined." (PMID 31627190, 2019). "It is the case of collagen type VI alpha 6 (COL6A6) that inhibits cell proliferation, migration, invasion, and epithelial-mesenchymal transition (EMT) through the binding of P4HA3 resulting in PI3K-Akt axis inhibition in pituitary adenomas." (PMID 33790868, 2021).
atopic dermatitis (3 papers, 2015 to 2018). "Three variants of the COL6A6 gene appeared in all three families and were in close proximity to atopic dermatitis-related loci on chromosome 3q21." (PMID 28125976, 2017). "Our study suggests that COL6A6 variants may be risk factors for atopic dermatitis." (PMID 28125976, 2017). "COL6A6 may regulate epithelial cell-fibronectin interactions, and variation in this gene may be identified in skin diseases, such as early-onset atopic dermatitis." (PMID 30577800, 2018). "KRT16 and COL6A6 were up-regulated in atopic dermatitis skin while the rest were down-regulated." (PMID 26717000, 2015).
head and neck squamous cell carcinoma (2 papers, 2022). A squamous cell carcinoma that arises from any of the following anatomic sites: lip and oral cavity, nasal cavity, paranasal sinuses, pharynx, larynx, and salivary glands. "It promoted cell proliferation, invasion and migration in head and neck squamous cell carcinoma and melanoma cells and reduced the anti-tumor activity of COL6A6 on growth and metastasis of AtT-20 and HP75 melanoma cells due to an action on PI3K-Akt signaling." (PMID 35846138, 2022).
lung carcinoma (2 papers, 2021 to 2024). "However, as a new member of the COL6 family, the role of COL6A6 in lung cancer is unclear." (PMID 33747955, 2021). "Finally, EIF4G1 displays diverse interactions in LUSC, linking with LUAD-related ZFHX4, COL6A6, and unusual PLPPR3 connections to lung cancer genes." (PMID 38389572, 2024). "However, no previous studies have reported on COL6A6 in lung cancer." (PMID 33747955, 2021).
atherosclerosis (1 paper, 2024). A disease characterized by the build-up of fatty material and calcium deposition in the arterial wall resulting in partial or complete occlusion of the arterial lumen. "In a previous study, we utilized phage display library techniques and bioinformatics analysis to identify COL6A6 as a novel protective antigen associated with atherosclerosis from the serum of patients with the condition." (PMID 39329770, 2024). "In this study, a synthesized COL6A6 peptide was obtained from the peripheral blood of atherosclerosis patients." (PMID 39329770, 2024). "In this study, a vaccine prepared with COL6A6 peptide (named the Pep_A6 vaccine) was administered to immunize Apoe−/− mice, and the immune mechanism of the Pep_A6 vaccine against atherosclerosis was first investigated." (PMID 39329770, 2024). "However, the specific immune mechanism by which the COL6A6 peptide vaccine provides protection against atherosclerosis remains unclear." (PMID 39329770, 2024). "Due to its multifaceted effects, the Pep_A6 vaccine, consisting of a COL6A6 peptide-KLH-conjugate and alum adjuvant, may serve as a promising vaccine formula in the future treatment of atherosclerosis." (PMID 39329770, 2024).
diabetes (1 paper, 2020). "FFour independent regions in the genome showed evidence of association with progression to diabetes: one region attaining genome-wide significance, 20p12.1 (TASP; P < 5 x 10–8) and three regions with suggestive evidence (P < 8.5 × 10–8), 1q21.3 (MRPS21-PRPF3), 2p25.2 (NRIR), and 3q22.1 (COL6A6)." (PMID 33154504, 2020).
endometrial cancer (1 paper, 2023). Primary or metastatic malignant neoplasm involving the endometrium (mucous membrane that lines the endometrial cavity). "Overexpression of collagen-associated genes (COL4A4, COL19A1, COL6A6) occurs in the late stages of endometrial cancer, which could indicate that they partake in the progression of EC." (PMID 36982551, 2023).
fibrosis (1 paper, 2021). the formation of excess fibrous connective tissue in an organ or tissue in a reparative or reactive process. "Col4a5, Col6a6, and Fn1 genes in charge of producing collagen of ECM components and markers of iWAT fibrosis, were discovered to be uniquely decreased in cold." (PMID 34017267, 2021).
ischemia (1 paper, 2022). A hypoperfusion of the BLOOD through an organ or tissue caused by a PATHOLOGIC CONSTRICTION or obstruction of its BLOOD VESSELS, or an absence of BLOOD CIRCULATION. "Contrarily, Col6a6, Col13a1, and Col25a1 genes showed no augmentation in mRNA expression at chronic phases of ischemia." (PMID 36555255, 2022).
lung adenocarcinoma (1 paper, 2021). A carcinoma that arises from the lung and is characterized by the presence of malignant glandular epithelial cells. "However, the functional role of COL6A6 in immune cell infiltration and prognostic value in lung adenocarcinoma (LUAD) remains unknown." (PMID 33747955, 2021).
lymph node metastasis (1 paper, 2021). "COL6A6 expression was negatively associated with pathological stage, tumor stage, and lymph node metastasis." (PMID 33747955, 2021).
Obesity (1 paper, 2024). Accumulation of substantial excess body fat. "COL6A6, NMI, Solibacillus, norank_f__Saccharimonadaceae, Candidatus_Saccharimonas, and unclassified_f__Butyricicoccaceae may represent novel discoveries linked to obesity." (PMID 38399773, 2024). "These communities may potentially interact with genes, including COL6A6 and NMI, thereby influencing the onset and progression of obesity." (PMID 38399773, 2024).
pituitary tumour (1 paper, 2022). "COL6A6 upregulation significantly inhibits the proliferation, invasiveness, migration and epithelial-mesenchymal transition (EMT) of pituitary tumour cells and significantly inhibits tumour size, tumour volume and tumour weight." (PMID 35292033, 2022).
sarcoidosis (1 paper, 2025). Sarcoidosis is a multisystemic disorder of unknown cause characterized by the formation of immune granulomas in involved organs. "However, unlike NL and NXG, COL4A4, COL6A6, and COL11A1 were not significantly upregulated in sarcoidosis fibroblasts, and CCL5 was only modestly upregulated." (PMID 39989459, 2025).
type 1 diabetes (1 paper, 2020). "We identified one novel region, 20p12.1 (TASP1; genome-wide P < 5 × 10–8) and three regions, 1q21.3 (MRPS21–PRPF3), 2p25.2 (NRIR), 3q22.1 (COL6A6), with suggestive evidence of association (P < 8.5 × 10–8) with progression from islet autoimmunity to type 1 diabetes." (PMID 33154504, 2020).
tumor (15 papers, 2015 to 2025). "Immunohistochemistry of primary tumor tissue was performed for eight proteins: COL6A6, DCD, GBP4, KLHL41, KRT9, PIP, SCGB1D2, SCGB2A2." (PMID 34757537, 2022). "Indicated that that COL6A6 was a tumor suppressor gene in NSCLC and was involved in NSCLC tumorigenesis by regulating the JAK signalling pathway." (PMID 35488336, 2022). "COL6A6 overexpression significantly suppressed tumor growth and metastasis capacity in pituitary adenoma." (PMID 33747955, 2021). "To obtain a deeper understanding of the relationship between COL6A6 expression and tumor immune infiltrates, we further determined the proportions of 22 types of TILs in LUAD using CIBERSORTx." (PMID 33747955, 2021). "Mutations in other collagens, such as COL6A6, COL22A1, COL6A3, COL12A1, and COL14A1, were also noted in a variety of tumor types." (PMID 34584216, 2021). "According to the GEPIA2 results, the COL6A6 mRNA expression in LUAD tumor tissues was significantly lower than that in normal tissues (|log2(fold change) |>2, P<0.01)." (PMID 33747955, 2021). "Immunohistochemistry results demonstrated that upregulation of COL6A6 decreased the expression of Ki-67 in xenograft tumor tissues." (PMID 31627190, 2019). "Overexpression of COL6A6 noticeably inhibited the size of the tumor, tumor volume (all P<0.01) and tumor weight (all P<0.001) compared with the NC group." (PMID 31627190, 2019). "Taken together, these data suggested COL6A6 elevated inhibited tumor growth and metastasis in PA via interacting with P4HA3 and blocking the PI3K-Akt pathway." (PMID 31627190, 2019). "Furthermore, low expression level of COL6A6 (another anti-tumorigenic ECM) was significantly associated with advanced pathological stage and large tumor size." (PMID 40583063, 2025). "Together, these findings show that COL6A6 may play a pivotal role in the tumor immune microenvironment of LUAD." (PMID 33747955, 2021). "The typical immunohistochemistry result revealed downregulated COL6A6 expression in tumor tissues." (PMID 33747955, 2021). "Our findings highlight that COL6A6 is involved in tumor immunity, suggesting COL6A6 may be a potential immunotherapeutic target in LUAD." (PMID 33747955, 2021). "Univariate analysis showed that pathological stage (HR=1.604, P<0.001), tumor (T) stage (HR=1.537, P<0.001), lymph node (N) stage (HR=1.668, P<0.001), and distant metastasis (M) stage (HR=1.955, P=0.02), along with COL6A6 expression (HR=0.794, P=0.003) were significantly associated with OS." (PMID 33747955, 2021). "Moreover, western blotting analysis results showed that COL6A6 elevated markedly increased COL6A6 protein level in tumor tissues of PA mice model compared with the NC group (all P<0.01)." (PMID 31627190, 2019). "Overexpression of COL6A6 significantly suppressed tumor growth and metastasis capacity in PA." (PMID 31627190, 2019). "Furthermore, the effects of COL6A6 interacted with P4HA3 on tumor growth and metastasis in PA were substantiated in vivo." (PMID 31627190, 2019). "COL6A6 is downregulated in tumor tissue versus adjacent normal breast tissue in the Lebanese." (PMID 27857161, 2016). "COL6A6 may play a role in the tumor immune microenvironment of LUAD." (PMID 33747955, 2021). "Furthermore, COL6A6-elevated suppressed tumor growth and metastasis in PA." (PMID 31627190, 2019). "Collagen type VI alpha 6 chain (COL6A6), a novel collagen, has been considered as a tumor suppressor and therapeutic target in several tumors." (PMID 33747955, 2021). "Therefore, we speculated that COL6A6 may act as a tumor suppressor in LUAD." (PMID 33747955, 2021). "Of those collagens that were differentially regulated, all were down-regulated in patient-derived tumour samples compared to matched non-tumour samples, ranging from 1.7-fold for type I collagen α1 chain (COL1A1) to 18.1-fold for type VI collagen α6 chain (COL6A6)." (PMID 37397358, 2023).
tumor (continued). "Furthermore, we observed that overexpression of COL6A6 significantly decreased the size of the tumor compared with the control group (all P<0.001), while the size of the tumor with IGF-1 treatment was bigger than the COL6A6 overexpression group (all P<0.001)." (PMID 31627190, 2019). "COL6A6 was a negative correlation with tumor size and high grade." (PMID 31627190, 2019). "To further clarify the mechanism of COL6A6 regulated the growth and metastasis of PA cells, we assessed the effect of COL6A6 interacted with P4HA3 on the PI3K-Akt pathway, which plays an important role in regulating tumor development, tumor cells invasion and EMT." (PMID 31627190, 2019). "Our data also demonstrates significant up-regulation of COL11A1, COL10A1, MMP1 and MMP13, and significant down-regulation of COL6A6 and DLK1 in tumor relative to non-tumor adjacent breast tissue." (PMID 27857161, 2016).
cancer (6 papers, 2019 to 2025). A tumor composed of atypical neoplastic, often pleomorphic cells that invade other tissues. "CAFs that overexpress COL3A1 and COL6A6 are presumed to be less effective in promoting cancer progression compared to those that show low overexpression." (PMID 33562096, 2021). "We observed that a 7-day treatment with BZDRs downregulated anti-tumorigenic ECMs, S100B, COL6A6 and VIT, in both non-carcinoma (MCF10A) and carcinoma cells (MCF7 and MDA-MB231) (blue boxes, * p < 0.05; ** p < 0.01; *** p < 0.005)." (PMID 40583063, 2025). "LAMA1, CHAD, ITGA8, and COL11A1 consistently showed hypermethylation in more than half of cancer types; on the contrary, TNN, SPP1, COL6A6, and TNR consistently showed hypomethylation in more than half of types of cancer." (PMID 36311789, 2022).
infection (1 paper, 2011). The state of being infected such as from the introduction of a foreign agent such as serum, vaccine, antigenic substance or organism. "Other hits found in this screening that were categorized as secreted proteins, such as chemokine C-C motif ligand 4-like 1 (CCL4L1) and collagen type VI alpha 6 (LOC131873/COL6A6), could have direct implications on the course of infection." (PMID 21625474, 2011).
musculoskeletal diseases (1 paper, 2018). "However, in recent years, COL6A6 has been implicated as a susceptibility gene in musculoskeletal diseases." (PMID 30577800, 2018).
skin disorder (1 paper, 2021). Any deviation from the normal structure or function of the skin or subcutaneous tissue that is manifested by a characteristic set of symptoms and signs. "Furthermore, variation in COL6A6 has been implicated in skin disorders." (PMID 33562221, 2021).
COL6A6 also shares sentences with these, for which no sentence is quoted: breast carcinoma (3 papers); melanoma (2); myopathies (2); channelopathies (1); colon carcinoma (1); colorectal cancer (1); entropion (1); glioblastoma (1); glioma (1); Hepatic fibrosis (1); muscular dystrophies (1); osteosarcoma (1); pancreatic cancer (1); pituitary adenocarcinoma (1); pulmonary fibrosis (1); renal fibrosis (1); Ullrich congenital muscular dystrophy (1); X-linked ichthyosis (1).